ETV4 (ETS variant transcription factor 4)
Diseases named in the same sentence as ETV4 in open-access papers (continued):
Sharing a sentence is not in itself a finding about the gene and the disease.
prostate carcinoma (continued). "Also, there are some cases where the mechanism by which ETV4 is highly expressed in prostate cancer is not well-defined." (PMID 36289913, 2022). "However, molecular features, such as gene expression and signaling pathways, in ETV4-fusion-positive prostate cancers have not been fully elucidated." (PMID 36289913, 2022). "The small number of ETV4 subtypes among prostate patients and the short history of research on ETV4 rearrangement have limited understanding of the molecular features of ETV4 subtypes of prostate cancer and, in turn, have resulted in an absence of effective targeted therapy for these patients." (PMID 36289913, 2022). "We used two prostate cancer cell lines (MDA-PCa-2b and PC3) harboring co-overexpression of ETV1 and ETV4 to gain insight into their biological role in vitro, and found both specific and shared candidate target genes that may play a role in tumor aggressiveness in vivo." (PMID 25595908, 2015). "However, the role of ETV4 overexpression in prostate cancer has never been investigated in vivo." (PMID 32791988, 2020).
colorectal cancer (24 papers, 2005 to 2026). A primary or metastatic malignant neoplasm that affects the colon or rectum. "As expected, ETV4, which is significantly positively associated with Hymenobacter, has been identified as a biomarker for colorectal cancer by a previous study." (PMID 39924716, 2024). "For example, in colorectal cancer, we found the significant association pair Hymenobacter-ETV4." (PMID 39924716, 2024). "Increased expression of TOP2A has been previously associated with poor cancer-specific survival in MPNSTs, whereas increased expression of ETV4, a member of the Ets family of transcription factors, has been associated with shorter patient survival in colorectal cancer and gastric cancer." (PMID 18522746, 2008). "Consistently, ETV4 overexpression converted the epithelial phenotype to a mesenchymal-like phenotype in colorectal cancer cells." (PMID 41281746, 2025). "ERK kinase promoted phosphorylation of ETV4, leading to blockade of ETV4 ubiquitination and degradation in colorectal cancer." (PMID 40777122, 2025). "Taken together, NID1 is a pivotal downstream gene of ETV4/LOXL2 promoting aggressive phenotype in colorectal cancer." (PMID 41281746, 2025). "Collectively, these results indicated that ETV4 promotes colorectal cancer cells growth and invasion in vitro." (PMID 41281746, 2025). "For example, there have been reports of the promotion of colorectal cancer progression by cell division cycle-associated 5 (CDCA5) and the functional role of E26 transformation-specific (ETS) variant 4 (ETV4) in pancreatic cancer." (PMID 33519944, 2021). "For example, repression of ETV4 in colorectal carcinoma cells significantly impairs their invasive capacity, and several EMT markers and MMPs were downregulated in shETV4-expressing cells." (PMID 29996935, 2018). "In addition, we analyzed the level of PCNA in tumor samples by immunoblot and immunohistochemical staining, which affirmed that ETV4 promoted colorectal cancer proliferation in vivo." (PMID 41281746, 2025). "Consistently, LOXL2 knockdown could markedly inhibit the proliferation of ETV4-overexpression colorectal cancer cells, as evidenced by colony formation assays." (PMID 41281746, 2025). "Consistently, ETV4 could markedly enhance the proliferation of colorectal cancer cells, as evidenced by colony formation assays." (PMID 41281746, 2025). "To identify the molecular mechanism underlying the ETV4-mediated EMT and metastasis in colorectal cancer cells, we next leveraged our RNA-seq data and a series of key downstream genes associated with EMT were further confirmed, including MER3, MSX1, LOXL2, THRB, WISP2, COL11A1, ADRB2 and E2F2." (PMID 41281746, 2025). "However, the mechanism of how ETV4 mediates colorectal cancer cell proliferation and metastasis still needs to be further revealed." (PMID 41281746, 2025). "Taken together, these results confirmed that ETV4 could induce EMT in colorectal cancer cell lines." (PMID 41281746, 2025). "Next, we analyzed mRNA levels of CIC, ETV4, and YAP1 in colorectal cancer (HT-29) and melanoma (A375) cells, expressing sgCtrl, sgCIC1, or sgCIC2." (PMID 36198276, 2022). "We next to verify whether ETV4/LOXL2/NID1 induce EMT transformation and metastasis in colorectal cancer cells by activating ERK signaling pathway." (PMID 41281746, 2025).
melanoma (20 papers, 2011 to 2025). A malignant, usually aggressive tumor composed of atypical, neoplastic melanocytes. "Our study revealed a preferential and variable expression of ETV4 in melanoma cells, which exhibit heterogeneity in hallmark pathway activity." (PMID 41502516, 2025). "Conclusively, a specific ETV4-associated enhancer was identified in melanoma, and its causal role in cancer-related phenotypes was demonstrated." (PMID 38849954, 2024). "Previous research confirmed that abnormal expression of ETV4 was associated with melanoma heterogeneity." (PMID 37205199, 2023). "Furthermore, ETV4 played a key role in modulating multiple signaling pathways and was associated with immune regulation, particularly in melanoma and renal cell carcinoma, where its expression predicted immune responses." (PMID 40469297, 2025). "Nuclear expression of PEA3/ETV4 in melanoma may be directly linked to activation of a pro-metastatic program through activation of FAK (Focal adhesion kinase) genes." (PMID 27689402, 2016). "We found that patient mutations in COP1 or DET1 inactivated CRL4COP1/DET1 in melanoma cells, stabilized ETV1, ETV4, and ETV5, and conferred resistance to inhibitors of the MAPK pathway." (PMID 40643496, 2025). "Our findings identify ETV4 as a key transcriptional regulator of immune evasion in melanoma by controlling PD-L1 expression." (PMID 41502516, 2025). "Despite the favorable association with survival in transcriptomic datasets, functional studies suggest that ETV4 plays an oncogenic role in melanoma." (PMID 40469297, 2025). "In this study, we found that ETV4 upregulates PD-L1 transcription in melanoma, consistent with prior findings in liver cancer where ETV4 binds the CD274 promoter, with the −734 to −339 bp region being essential for transcriptional regulation." (PMID 41502516, 2025). "Our ligand-receptor-based cell communication analysis demonstrated increased interactions between ETV4-low melanoma cells and T cells, including TNFSF14-LTBR and IFNG-(IFNGR1+IFNGR2) signaling pathways." (PMID 41502516, 2025). "Immune checkpoint signaling modulates T cell function, and our RNA-seq analysis of SK-MEL-28 cells identified PD-L1 as the predominant immune checkpoint regulated by ETV4 in melanoma, consistent with findings in hepatocellular carcinoma." (PMID 41502516, 2025). "While a recent study has shown that ETV4 plays a role in melanoma cell proliferation and migration, our findings suggest a novel role for tumor ETV4 expression in melanoma progression through the regulation of tumor-immune cell interactions." (PMID 41502516, 2025). "We observed that ETV4 downregulation in melanoma cells rendered them more sensitive to T cell-mediated killing." (PMID 41502516, 2025). "scRNA-seq analysis showed that ETV4 is preferentially expressed in melanoma cells and involves in mediating tumor-immunocyte interactions." (PMID 41502516, 2025). "ETV4 expression in melanoma cells influences their crosstalk with T cells and impairs T cell-mediated tumor killing by upregulating PD-L1 expression." (PMID 41502516, 2025). "High pretreatment levels of ETV4 are indicative of low responsiveness to immune checkpoint inhibitors in melanoma patients." (PMID 41502516, 2025). "Malignant melanoma cells were classified into ETV4-high and ETV4-low groups based on the upper tertile of ETV4 expression." (PMID 41502516, 2025). "Together, we provided evidence to support the role of ETV4, whose expression is regulated by enh17, in the cell proliferation and migration of melanoma." (PMID 38849954, 2024). "This work sheds light on the regulatory mechanism and function of enh17 in melanoma, ETV4-enh17 represents a promising potential target for the prevention/ treatment of melanoma." (PMID 38849954, 2024). "Transcription factor STAT3 was found to bind to the enh17 region to promote the expression of ETV4, which ultimately contributes to promoting tumor progression in melanoma." (PMID 38849954, 2024).
melanoma (continued). "In the present study, STAT3, as a transcription factor, binds to enh17 to regulate the expression of ETV4, thereby inducing cell proliferation and migration in melanoma cells." (PMID 38849954, 2024). "More studies should focus on exploring ETV4 as a prognostic marker for melanoma and testing its potential value in melanoma treatment in the future." (PMID 38849954, 2024). "In this study, we newly characterized one enhancer element that was responsible for the regulation on ETV4 transcription in melanoma cells." (PMID 38849954, 2024). "We investigate a possible role for DUSP4 and ETV4 in mediating this response by assessing the effect of their depletion on the sensitivity of BRAF wild-type melanoma cells to MEK inhibition." (PMID 31839677, 2020). "Despite our findings that targeting ETV4 may potentiate anti-tumor immunity and improve responses to immune checkpoint blockade in melanoma, translating ETV4-targeted therapies into clinical practice presents a significant challenge." (PMID 41502516, 2025). "To further assess whether ETV4 levels influence immunotherapy efficacy in melanoma patients, we analyzed melanoma cohorts with available survival data and categorized data on ETV4 expression." (PMID 41502516, 2025). "Our analysis indicates that ETV4 may serve as a valuable predictor of immunotherapy outcomes, particularly in melanoma and KIRC." (PMID 40469297, 2025). "Moreover, we demonstrated that tumor ETV4 expression influences the crosstalk with infiltrating immune cells within the melanoma TME and affects the response to anti-PD-1 therapy, potentially due to its role in transcriptionally activating CD274 expression." (PMID 41502516, 2025). "In addition, we found that ETV4 has a predictive effect on the immunotherapy outcomes for melanoma and renal cell carcinoma, with high ETV4 expression indicating poorer responses to immunotherapy." (PMID 40469297, 2025). "Thus, our findings provide evidence that ETV4 is a key transcription factor promoting CD274 gene transcription in melanoma cells." (PMID 41502516, 2025). "Furthermore, we explored the preferential expression of ETV4 in melanoma cells within the TME and its possible involvement in mediating crosstalk between tumor cells and infiltrating immunocytes." (PMID 41502516, 2025). "Our study suggests that the association between pretreatment levels of ETV4 and the efficacy of anti-PD-1/anti-CTLA-4 therapy may be explained by the positive regulation of PD-L1 expression by ETV4 in melanoma." (PMID 41502516, 2025). "Both ETV4 knockdown and rescue experiments provide further evidence that ETV4 is involved in the regulation of cell proliferation and migration downstream of enh17 in melanoma cells." (PMID 38849954, 2024). "In addition to ETV4, there should be more target genes directly or indirectly regulated by enh17 during melanoma progression." (PMID 38849954, 2024). "Here, we infer that not only in CRC with MSS status but also in other cancer types, such as melanoma and other GI cancers, ETV4 may act as key functions." (PMID 33628843, 2021). "This interaction activates mitogen-activated protein kinase kinase kinase 8 (MAP3K8), also termed tumour progression locus 2 (TPL2), which conversely stimulates the transcription factor ETS translocation variant 4 (ETV4), leading to induction of MMP25 and promoting melanoma lung metastasis." (PMID 32722137, 2020). "We wished to extend this observation by ascertaining whether DUSP4 or ETV4 might also influence the response of wild-type BRAF melanoma cells to MEK inhibition." (PMID 31839677, 2020). "Additionally, we did not experimentally validate whether PD-L1 is the sole downstream mediator of ETV4-induced immune evasion in melanoma." (PMID 41502516, 2025). "In melanoma, several ETS TFs, including FLI1, SPI1, ELF4, ETV7, SPIB, and SPIC, are expressed at higher levels in Cluster A patients, whereas ETV5, ETV4, ELK1, ERF, and ETV2 showed increased expression in Cluster B patients." (PMID 41502516, 2025).
melanoma (continued). "In particular, ELK3, ETS1, ETV1, ETV4, ETV5, and SPI1 were significantly upregulated in melanoma, whereas EHF, ELF3, ELF5, ERG, ETS2, ETV7, and SPDEF were significantly downregulated in the tumor." (PMID 33424867, 2020). "We report here that two components of the MEK 6 gene score, ETV4 and DUSP4, were expressed at significantly higher levels in melanomas of responders to docetaxel plus selumetinib compared with those who progressed at first assessment." (PMID 31839677, 2020). "Whereas the role of TNC (tenascin C) and FN1 (fibronectin 1) in melanoma development is well documented, implication of MARCKS, RCN3, BAMBI, PEA3/ETV4 and the FK506 family members FKBP7, FKBP10 and FKBP11 in melanoma progression is unclear." (PMID 27689402, 2016). "In human melanoma cells, CIC represses mRNA expression of the PEA3 subfamily of ETS transcription factors, namely ETV1, ETV4 and ETV5." (PMID 26683696, 2015). "For example, ERG, ETV1, and ETV4 can be upregulated in prostrate cancers, and ETV1 is upregulated in post gastrointestinal stromal tumors and in more than 40% of melanomas." (PMID 26683696, 2015). "We validated the heterogeneity and aberration status within single biopsies by fluorescent in situ hybridization of four affected and transcriptionally up-regulated genes E2F8, ETV4, EZH2 and FAM84B in 11 melanoma cell lines." (PMID 21569352, 2011). "To test whether ETV4 expression contributes to tumor resistance to T cell killing, we extracted T cells from human peripheral blood and cocultured them with SK-MEL-28 melanoma cells." (PMID 41502516, 2025). "In melanomas of patients on the selumetinib but not the placebo arm, two gene signature components, dual-specificity protein phosphatase 4 (DUSP4) and ETS translocation variant 4 (ETV4), were expressed more highly in responders than non-responders." (PMID 31839677, 2020). "However, the oncogenic function of ETV4 in melanoma has not been systematically reported, and how ETV4 expression is regulated in tumor initiation and progression is poorly understood." (PMID 38849954, 2024). "In melanoma, the polyoma enhancer activator 3 (PEA3) subfamily, particularly ETV4 and ETV5, showed a negative correlation with immune infiltration." (PMID 41502516, 2025). "Downstream signaling analyses showed that MCAM drives the activation of ETV4, which in turn modulates the expression and activity of ZEB1 but not MMP25 observed in melanoma." (PMID 40924339, 2025).
lung carcinoma (18 papers, 2010 to 2025). "The ETV4 P433L mutations site was introduced into lung cancer cell lines, resulting in altered migration and stem-like properties of the cancer cells." (PMID 39389944, 2024). "Our findings further support the notion that activation of Wnt/β-catenin pathway in ETV4 P433L mutation cells promotes the acquisition of stem-like properties in lung cancer cells compared to wild-type ETV4 cell." (PMID 39389944, 2024). "Meanwhile, we aimed to investigate the potential mechanism of wild-type and ETV4 P433L mutation lung cancer cell lines." (PMID 39389944, 2024). "In order to further investigate the role of the ETV4 P433L germline mutation in lung cell lines A549 and H322, we constructed wild-type and mutant-type (P433L) ETV4 based on sh1-ETV4 expression downregulated lung cancer cell lines." (PMID 39389944, 2024). "Additionally, we examined the biological implications of the ETV4 P433L mutation in lung cancer through in vitro and in vivo experimentation." (PMID 39389944, 2024). "The ETV4 P433L mutation could impact the stem-like properties and migration of lung cancer through Wnt/β-catenin signaling pathway." (PMID 39389944, 2024). "Therefore, it remains uncertain whether the ETV4 P433L mutation is exclusively associated with MPLC or if it also plays a role in other types of lung cancer." (PMID 39389944, 2024). "Future work should further investigate the benefit of TOP1 and other inhibitors in treating lung cancer addicted to ETV4‐overexpressed transcription and replication across panels of cell lines, patient‐derived organoids, and in vivo experimental test." (PMID 40548893, 2025). "As directly targeting ETV4 is challenging, our findings present an exciting alternative strategy to exploit TOP1 as novel targets in ETV4‐dysregulated lung cancers." (PMID 40548893, 2025). "Here, it is shown that oncogenetic ETS transcription factor ETV4 controls DNA replication through both transcriptional and non‐transcriptional mechanisms in non‐small cell lung cancer (NSCLC)." (PMID 40548893, 2025). "Our investigation confirmed that suppressing ETV4 expression in lung cancer cell lines significantly decreased tumor proliferation and migration ability, and downregulated the expression of stemness genes." (PMID 39389944, 2024). "The regulatory function of SOX4, FOXM1, and ETV4, over other key TFs and common DEGs, was highlighted in lung cancer, establishing key co-regulatory complexes in NSCLC and SCLC." (PMID 39228892, 2024). "A recent report revealed that a transcriptional repressor CIC (also known as Capicua) suppresses invasion and metastasis of mouse lung cancer through inhibition of the expression of Etv4 and its target gene MMP2449." (PMID 28446749, 2017). "Interestingly, knockdown of either ETV4 or ETV5 strongly inhibited the growth of human KRAS-mutant lung cancer cell lines, suggesting that the requirement for these transcription factors extends to human lung cancer." (PMID 41219537, 2025). "ETV4-driven EMT has also been described in lung cancer and thyroid carcinoma." (PMID 40469297, 2025). "Furthermore, in vitro experimental results demonstrate the enhanced efficacy of CPT on cell survival in the context of ETV4‐overexpressed lung cancers." (PMID 40548893, 2025). "According to the TRN analysis, SOX4 can be regulated by HOXC6, whereas DLX5 can be regulated by SOX4, FOXM1, and ETV4, and according to the co-regulatory network analysis, they both participate in the formation of TF complexes in both subtypes of lung cancer (NSCLC and SCLC)." (PMID 39228892, 2024). "The TCGA datasets provided evidence of high expression of ETV4 in lung cancer tissues." (PMID 39389944, 2024). "Taken together, these findings support the idea that ETV4 could increase the stemness of lung cancer cells." (PMID 26356813, 2015). "As targeting ETV4 directly is challenging, our findings present an exciting alternative strategy to exploit TOP1 as novel targets in ETV4‐dysregulated lung cancers." (PMID 40548893, 2025).
lung carcinoma (continued). "The global transcriptomic network analysis highlighted the impact of five TFs, SOX4, TCF3, TEAD4, ETV4, and FOXM1, in gut and lung cancer." (PMID 39228892, 2024). "According to the TRN of lung cancer, SOX4, FOXM1, ETV4, HOXC6, and E2F3 are the main positive regulators, whereas SOX17, KLF4, and ZBTB16 are the main negative regulators of transcription, controlling the expression of other TFs and target genes in lung cancer." (PMID 39228892, 2024).